RNU2-13P (RNA, U2 small nuclear 13, pseudogene)
Gene: Small nuclear RNA gene on chromosome 2 (11,561,194 to 11,561,306, forward strand). Ensembl gene ENSG00000251718.
Homologues: Orthologues: guinea pig U2 (64% identical), guinea pig U2 (62% identical), rabbit U2 (60% identical), dog U2 (58% identical), pig U2 (52% identical), rat LOC120101110 (52% identical), guinea pig U2 (51% identical), macaque U2 (51% identical), zebrafish U2 (50% identical), guinea pig U2 (50% identical), guinea pig U2 (49% identical), guinea pig U2 (46% identical), and 2 more. Paralogues in human: RNU2-2 (74% identical), U2 (74% identical), RNU2-56P (73% identical), U2 (73% identical), RNU2-3P (73% identical), RNU2-6P (73% identical), RNU2-36P (72% identical), RNU2-48P (72% identical), RNU2-59P (72% identical), RNU2-8P (72% identical), RNU2-14P (71% identical), RNU2-25P (71% identical), and 65 more.